CD4 (CD4 molecule)
Diseases named in the same sentence as CD4 in open-access papers (continued):
Sharing a sentence is not in itself a finding about the gene and the disease.
tumor (continued). "In particular, tumor antigens released by destroyed cancer cells are processed by APC cells and presented to the CD4+ and CD8+ lymphocytes triggering the immune response that improve tumor destruction." (PMID 33902630, 2021). "The increased recruitment of macrophages, DC, and endogenous CD4+ and CD8+ T cells to lymphatic tissues was observed, along with the recruitment of DC, CD4+, and CD8+ T cells to the tumor." (PMID 35008832, 2021). "We performed a meta-analysis of 11 studies with a total of 1398 patients with LSCC, in which TIL were quantified either immunohistochemically for CD8+, CD4+, and/or CD3+, or in HE-stained sections in tumor epithelium and/or tumor stroma." (PMID 33925205, 2021). "The study also implies that the CD4+ T cells indirect recognize tumor, and direct recognition of the citrullinated epitopes on MHC class II in the tumor is more potent for cancer therapy." (PMID 34671213, 2021). "Inhibition of TGFβ plus immune checkpoint blockade led to Th1 CD4+ T cell responses and the clonal expansion of CD8+ T cells in bone tumors, which improved anti-tumor responses and increased survival in mice." (PMID 34502458, 2021). "It was noticed that the percentage of CD3+TIGIT+ T(53.89 ± 14.05), CD4+TIGIT+ T(54.88 ± 18.56) and CD8+TIGIT+ T cells (52.03 ± 7.65) were significantly increased in tumor tissues when compared with peripheral blood samples." (PMID 34659197, 2021). "DPP4 expression showed significant correlations with tumor purity in LUSC and significant correlations with the infiltration of B cells, CD8+ T cells, CD4+ T cells, macrophages, neutrophils, and dendritic cell." (PMID 33614513, 2021). "Tumor cells typically exhibit a CD2+/−, cytoplasmic CD3+, CD4−, CD7+, CD8−, CD56+, CD103−, and TIA1+ phenotype." (PMID 34830926, 2021). "Inhibiting CD39 or CD73 by small-molecule inhibitors or blocking antibody markedly reduced the inhibition of CD4+ and CD8+ T cell responses and meanwhile elevated the cytotoxic activity of CTL and NK cells, resulting in tumor cells being killed." (PMID 33413697, 2021). "PD-L1+ tumours displayed higher IT and PT CD8+/PD1+ cell density compared to PD-L1- (p < 0.05), and primary IT infiltrate was enriched in CD4+/FOXP3+ cells, compared to PT regions (p = 0.004)." (PMID 33946676, 2021). "Conventional DCs (cDC) are classified into two subsets, cDC1 and cDC2, and their primary function is to acquire tumor antigen, migrate into lymph nodes, and prime CD8+ and CD4+ T cells, respectively." (PMID 34921160, 2021). "It has been identified that CD4 and CD8+ TILs and tumor cells obtained from lesional skin samples in MF cases show increased co-expression of the typical exhausted T cell surface markers PD-1, TIGIT, and TIM-3." (PMID 34685762, 2021). "Within the T cell compartment, levels of CD4 + T cells, CD8 + T cells, and Tregs vary greatly across tumor models, with KRIMS-2 tumors showing high divergence from UPS primary and KRIMS-1 tumors." (PMID 33441747, 2021). "DC-derived exosomes can be loaded with several peptide antigens (e.g., MHC I, MHC II) in the presence of APC, thereby stimulating CD4+ helper T cells and CD8+ CLTs to induce the anti-tumor response." (PMID 34722637, 2021). "Compared with the level of immune cells in the peripheral blood and the infiltration of immune cells in the tumor microenvironment, CD4+T cells and CD19+B cells showed the opposite trend in peripheral blood and in the tumor microenvironment." (PMID 34258299, 2021). "Characterization of the PDOTSs showed that autologous tumor‐infiltrating T lymphocytes (CD3+, CD4+, and CD8+) were retained during short‐term in vitro culture." (PMID 34240815, 2021). "Compared to control group, the percentage and the number of CD4+ T and CD8+ T cells in PRMT5 knockdown tumor microenvironment were significantly higher." (PMID 34522232, 2021).
tumor (continued). "In contrast, CD4+ regulatory T cells (Treg) within the TME, which can suppress, for example, CTL or Th1 responses, are thought to interfere with effective anti-tumor immunity and therefore considered as indicators of a poor clinical outcome." (PMID 34073258, 2021). "Genetic or pharmacologic disruption of HDAC6 in CAFs delays tumor growth, inhibits tumor recruitment of MDSCs and Tregs, alters macrophage phenotype switch, and increases CD8+ and CD4+-T cell activation in vivo." (PMID 34337083, 2021). "CD4+ T cells and CD8+ cells can prevent the tumor from developing by capturing tumor antigens and activating adaptive immunity to kill tumors." (PMID 34512816, 2021). "Since the depletion of MDSCs and TAMs was anticipated to result in an increase in the Teff response to the 4T1 tumor, we investigated the effect of DABIL‐4 administration upon both CD4+ and CD8+ lymphocytes in 4T1 tumor‐bearing mice." (PMID 33682324, 2021). "Evidence suggests that in MPM, adaptative immune cells—CD4+ helper T-cells and CD8+ cytotoxic T-cells—are mainly expressed in the stromal compartment of the tumour, whereas regulatory T-cells border the tumour cells." (PMID 34206956, 2021). "Significant elevations (p < 0.05) in CD4 + T, CD4 + helper T, Treg, and NKT cells were found in tumor and blood in SPD or combination treatment compared to controls or anti-mCTLA-4." (PMID 34331595, 2021). "The tumours of control and pHIFU + ICI-treated subjects showed that 2 ± 1% and 3 ± 1% of their live cells were CD3+CD4+FoxP3+, respectively, and 7 ± 4% and 10 ± 4% were CD11b+Ly6G+, respectively." (PMID 34229458, 2021). "For instance, TILs, such as CD4 + T cells and CD8 + T cells, play an essential role in tumor dissemination, relapse, metastasis, and therapeutic response to immunotherapy." (PMID 34513843, 2021). "Conversely, M2 polarization prevents the production of cytokines required to support tumor-specific CD8+ T cells, and CD4+ T helper 1 (Th1), promoting tumor proliferation." (PMID 33917013, 2021). "Ipilimumab was evaluated in urothelial BC patients and showed an increase in CD4+ and CD8+ T cells in both tumor and blood, thus increasing inflammatory cytokine signature." (PMID 33802203, 2021). "Anti-CTLA-4 mAbs were initially thought to suppress the inhibition on activated CD4+ and CD8+ T cells and augment the anti-tumor immune response in the TME." (PMID 34806028, 2021). "If we look at early tumor structure, there are small tumors with many CD3, CD8, CD4, memory T cells, and tertiary lymphoid organs (TLO) at the invasive margin and in the tumor center." (PMID 35008550, 2021). "Our findings in relation to CD4 and CD8 are in keeping with the prognostic benefit of these immune cell types observed in other tumours." (PMID 33481339, 2021). "In tumor immunity, CD4 T cells can activate cytotoxic T lymphocytes (CTLs) through a variety of mechanisms to maintain and strengthen the antitumor response of CTLs, while the presence of infiltrating Tregs may be detrimental to the host defense against the tumor." (PMID 33714943, 2021). "In a mouse breast cancer model of 4T1, cationic polysaccharide spermine modified pullulan (PS) was internalized into lysosomes of macrophages and reprogramed M2 macrophages to M1, which increased CD4+ and CD8+ T cells and inhibited tumor progression." (PMID 33990205, 2021). "CD4+ T cells secrete cytokines to recruit and activate other immune cells, while CD8+ T cells have cytotoxic functions and can directly kill infected or tumor cells." (PMID 34905486, 2021). "Whereas the majority of CD3+ T cells in the spleens were CD4+ (80%), more than 75% of them were CD8+ T cells in the tumours." (PMID 34262856, 2021). "There was a considerable increase in CD8+ cells, CD4+ cells, and NK cell populations in CPV2.NS1 treated group generating a strong anti-tumor immune response." (PMID 34012915, 2021).
tumor (continued). "In order to determine local immune infiltration patterns in the tumor, CD8+ T cells, CD4+ T cells and tumor cells were first detected by an automated image processing pipeline." (PMID 33791196, 2021). "Cancer neoantigens are present exclusively in tumor cells and not in normal cells and have been shown to play a significant role in recognition and killing of tumor cells by CD8 and CD4 T-cell mediated immune responses." (PMID 34452005, 2021). "Inhibition of PI3Kγ appears to sensitize tumors to anti-PD-1 antibody therapy and to slow tumor growth by increasing the level of CD4+ and CD8+ T lymphocytes within the tumor." (PMID 34885109, 2021). "TANs alter macrophage polarization, recruit and activate CD4+ and CD8+ T cells, promote tumor cell sloughing from basement membranes, induce direct tumor cell apoptosis by secreting cytotoxic ROS, and can even elicit antibody-dependent cell cytotoxicity." (PMID 33670082, 2021). "Kaplan-Meier curves showed that patients with higher abundance of tumor-infiltrating B cells, CD8+ T cells, CD4+ T cells, macrophages, neutrophils and dendritic cells had shorter overall survival in LGG." (PMID 33391455, 2021). "On day 4 post-treatment, tumor tissue sections were analyzed using immunofluorescence microscopy for immune cell markers such as CD3, CD4, and CD8 for the assessment of the level of infiltrating T cells in the tumor tissues." (PMID 33538860, 2021). "PD-L2 was shown to be moderately or strongly expressed in most tumor cells, to interact with PD-1 and to dramatically inhibit TCR-mediated proliferation, CD4+ T cell cytokine production and T-cell cytolysis." (PMID 34289871, 2021). "We analysed the CD3+ T-cells functional states from PDAC tumours using differentiation, activation and checkpoint markers, to characterise the CD8+, CD4+ and Treg compartments." (PMID 33917832, 2021). "αGITR treatment converts immunosuppressive Treg cells into anti-tumor Th1-like CD4 T cells and cooperate with CD8 T cells in killing GBM tumor cells through TCR-MHC engagement-dependent mechanisms." (PMID 33976133, 2021). "Our previous findings have demonstrated that IL-21-producing CD4+ T cell ACT augments the effector CX3CR1+ CD8+ TIL population, resulting in enhanced tumor control." (PMID 33809259, 2021). "Tumor sections made at cycle 2, 3 and 4 were processed using antibodies reacting with Ki-67, CD45, CD4 and CD8." (PMID 33664349, 2021). "Further, this antitumor response resulted in a more dramatic improvement of CD4+, CD8+, and NK cell infiltration into the tumor." (PMID 34439192, 2021). "Recently, we showed that inhibition of NR2F6 gene function improves CD4+ and CD8+ T cell infiltration in addition to effector functions at the tumor site in different mouse tumor models." (PMID 34073258, 2021). "The results of scRNA-seq analysis showed that rAAV-P2 treatment can increase the proportion of CD4+, CD8+ T cells, and NK cells in the tumor, suggesting an increased lymphocyte infiltration in 4T1 tumors." (PMID 34887423, 2021). "This study calculated estimations of CD4+, CD8+ and tumor-infiltrating lymphocytes (TILs) for glioma, MB, ATRT and EPN methylation data." (PMID 34830753, 2021). "NPC-derived exosomes carrying C15 can transform CD4+CD25- T lymphocytes into Treg cells (CD4+CD25+) and stimulate Treg cell aggregation and immunosuppressive effects, allowing tumor cells to escape immune clearance." (PMID 34566954, 2021). "Orthotopic rodent and murine bladder tumors treated with BCG (Pasteur, Connaught and Tice) were shown to recruit both CD4 and CD8 T cells that recognized ‘tumor antigens’ overexpressed in the tumor cell line and BCG antigens." (PMID 34944584, 2021). "Moreover, many tumor cells lack MHC class II expression, so the effects of cytotoxic CD4+ T cells may be less relevant for these tumors or may rely on bystander killing on antigen-presenting cells, which could also lead to immune modulation with the tumor." (PMID 34910940, 2021).
tumor (continued). "Modern technologies have enabled identification of tumor-specific, MHC-I and -II restricted neoantigens and detection of CD8+ and CD4+ T cells responding to such neoantigens." (PMID 35097027, 2021). "The majority of the Tumor-infiltrating lymphocytes (TILs) are represented by CD8+ CTLs, CD4+ T helper cells, and by regulatory CD4+/FoxP3+ T-cells (Tregs)." (PMID 33804731, 2021). "After initial tumor control, the patient relapsed, and a second cell transfer with enriched anti-ERBB2IP CD4+ T cells led to durable clinical response." (PMID 33546283, 2021). "LCP2 expression was correlated with tumor-infiltrating B cell, CD8+ T cell, CD4+ T cell, macrophage, neutrophil and dendritic cell in SKCM-Metastasis cohorts." (PMID 33911146, 2021). "As observed in tumor-free mice, KISIMA–STINGa combination treatment modulated the polarization of intra-tumoral CD4 T cells, decreasing the presence of Tregs while increasing the Th1/Th2 ratio." (PMID 34276686, 2021). "Another study reported that EBV tumours were most infiltrated with CD8+ CTL and macrophages (28% and 22% of all intratumoural cells, respectively), with an intermediate frequency of CD4+ T cells (20%) and low rate of Tregs (4%)." (PMID 34956172, 2021). "The degrees of infiltration of CD4+ and CD8+ T cells in the tumors of immunocompetent mice were examined and indicated that the number of tumor-infiltrating CD8+ T cells was markedly increased after treatment with the TBK1 antagonist." (PMID 33679751, 2021). "Tregs represent a critical subset of CD4 T-cells, characterized by CD4 + CD25 + Forkhead box P3+ (FoxP3+) phenotype, able to control peripheral tolerance as well as response to foreign and tumor antigens." (PMID 34640606, 2021). "Generally, most of the algorithms showed that m6A score was negatively correlated with anti-tumor immune cells, including CD8 T cells, CD4 T cells, and natural killer T cell." (PMID 33816290, 2021). "The results obtained from our TIMER and CIBERSORT analysis demonstrated that there was a significant association between the level of TACC3 expression and the degree of tumor infiltration by B cells, CD8+ T cells, CD4+ T cells and DCs in KIRC tissues." (PMID 33714201, 2021). "CD4+ T cells act in a bidirectional regulatory network with B cells to induce differentiation of B cells which in turn, stimulates CD4+ TH1 and TH2 differentiation, suggesting the clinical significance of these immune cells for anti-tumor response." (PMID 34012451, 2021). "Using SAR405 decreased the tumour growth and improved mouse survival in multiple tumour models by inducing tumour infiltration of NK, CD8+, and CD4+ T effector cells and repressed viability of liver cancer stem cells." (PMID 34706732, 2021). "Tissue sections from the RBE-circHMGCS1–016 humanized mice treated by IgG and PD1 antibodies contained fewer tumor-infiltrating CD8+ and CD4+ lymphocytes than other groups." (PMID 34526098, 2021). "Heterogeneity is observed among CD4+ and CD8+ T‐cells; however, more emphasis has been placed on CD8+ cells as they are believed to play the major role in the effector stage of tumour cell killing." (PMID 33846997, 2021). "Immunohistochemical staining of cholangiocarcinoma specimens reveals variable localization of distinct subsets of TILs within the tumor; CD8+ TILs prevail in the intratumoral region, whereas CD4+ T cells are prevalent across the peritumoral area." (PMID 33922362, 2021). "We recently performed transcriptomic profiling and comparative analyses of sorted CD4+ and CD8+ tumor-infiltrating lymphocytes (TILs) from bulk tumors of CRC patients with varying disease stages." (PMID 33916009, 2021). "Additionally, CD4+ T cells may exert direct anti-neoplastic activity through production of pro-inflammatory cytokines or execution of cytotoxic signals on tumor cells and aid in B cell mediated humoral anti-tumor responses through CD40L signaling." (PMID 35097027, 2021).
tumor (continued). "CD4+ T cells relay help signals to CD8+ T cells to optimize the magnitude and quality of the response of cytotoxic T lymphocytes (CTLs) within tumor sites." (PMID 34660573, 2021). "IDO1 expression levels in CESC were negatively correlated with tumor purity and macrophages but positively correlated with CD8+ and CD4+ T cells, neutrophils, and dendritic cells." (PMID 34778035, 2021). "Data from the NCT00715014 trial of neoadjuvant Sipuleucel-T shows that DC vaccination does lead to increased recruitment of T cells including CD4+, CD8+, and T-regs into the tumor." (PMID 33854509, 2021). "We analyzed the correlations between each CXC and tumor purity, B cells, CD8 + T cells, CD4 + T cells, macrophages, neutrophils, and dendritic cells in three types of cancer." (PMID 34439306, 2021). "PD1, TIM3, LAG3, and CTLA4, expressed on the surface of CD4+ and CD8+ T cells, indicate the occurrence of tumor immune escape phenomenon in PVNS pathogenesis." (PMID 34248943, 2021). "Both CD4_5 and CD4_7 had expression of regulatory T (Tregs) cell markers, with higher levels of FOXP3, IL2RA (CD25), CTLA4, and TNFRSF18 (GITR) in the tumor-predominant CD4_5." (PMID 33504936, 2021). "In gliomas, this immunosuppression is bolstered by the upregulation of PD-L1 on tumor cells and circulating monocytes/macrophages, which further inhibits CD8+ and CD4+ T cell activation." (PMID 34054867, 2021). "GSK126 reduces anti-tumour immunity by increasing the number of myeloid-derived suppressor cells, leading to fewer CD4+ and CD8+ T cells in the tumour microenvironment." (PMID 33391954, 2021). "In this study, the proportion of CD4+ T cells remained stable in model mice, while that of CD8+ T cells was increased by PD-L1 inhibitor and inhibited by CircCHST15 in the mouse tumor, and PD-L1 inhibitor reversed the effect of CircCHST15." (PMID 33777742, 2021). "For example, chemokines (CXCL9 and CXCR3) can exert antitumor responses by recruiting CD4+ T cells, CD8+ T cells, NK cells and M1 macrophages into the tumor center." (PMID 34335575, 2021). "scRNA-Seq revealed exhaustion, tumor residency, and late differentiation signatures in CD39+ CD4 TILs." (PMID 33332284, 2021). "In the T cell–tumor co-cultured assay, A375 cells, MDA-MB-231 cells, and HEK293T-hPD-L1 cells expressed human PD-L1, binding to PD-1 on CD4+ T cells to suppress the function of T cells." (PMID 34912719, 2021). "The results were consistent with other studies that monocyte immune cells such as B cells, CD4 + T cells, CD8 + T cells, macrophages, and natural killer (NK) cells played a key role in tumor immunity and were also related to tumor prognosis in HNSCC patients." (PMID 34490269, 2021). "In fact, the pattern of elevated PD-1 and decreased CD69 was observed on CD103+ CD4 or CD8 TILs, linking tumor residency to specific degree of TIL activation status." (PMID 34680397, 2021). "In fact, while CD4+ lymphocytes upregulate A20 and NFKB1 genes over-time when embedded in tumor 3D constructs, CD8+ lymphocytes immediately downregulate most NF-kB genes." (PMID 34070750, 2021). "TIM-3 mainly inhibits the functions of CD4+ and CD8+ T cells, and helps tumor cells escape from the immune system." (PMID 34938753, 2021). "Both CD4+CD8α+ and CD4+CD8αβ+ TEG011 cells secreted significantly higher levels of IFNγ upon exposure to tumor targets than CD4+ TEG011 cells." (PMID 34759930, 2021). "Histopathologic analysis indeed revealed the presence in B16-F10 tumours of CD8+ and CD4+ T cells, CD31+ microvessel structures, α–smooth muscle actin (α-SMA)–positive CAFs, and collagen (stained with Sirius red)." (PMID 33299131, 2021). "In the first phase, immune system components such as natural killer cells (NK cells), as the innate arms of the immune system, together with T CD4+ and T CD8+ cells, as the adaptive arm of the immune system, can succeed in eradicating tumor cells." (PMID 34572263, 2021).